IL1B (interleukin 1 beta)
Diseases named in the same sentence as IL1B in open-access papers (continued):
Sharing a sentence is not in itself a finding about the gene and the disease.
infection (continued). "Finally, COX-2 catalysis promoted by interleukin 1(IL-1β) yields increased levels of the reaction product PGE2, which cooperates with IL-1β to limit excessive type I interferon (IFN) production and prevent the death of Mtb-infected mice during the acute phase of infection." (PMID 35766265, 2022). "Furthermore, compared with the control group, vB_CbrM_HP1 administration resulted in a decrease in cytokine (TNF-α, IFN-γ, IL-1β) levels which was the same phenomenon as seen in the phage PIZ SAE-01E2 and the phage AVP in the treatment of infection with S. abortus equi and A. viridans, respectively." (PMID 35601403, 2022). "Likewise, GSDMD is necessary for the release of cleaved IL-1β during infection but is not required for IL-1β processing within cells." (PMID 35563469, 2022). "In line with our in vivo results and regardless of strain genetic background, infection with ∆T mutant strains resulted in significantly higher levels of IL-1β and IL-18 secreted by BMDMs, and complementing ∆T strains with pExoT reduced the production of these pro-inflammatory cytokines." (PMID 35277504, 2022). "We found that the Lro isolate (both untreated and with the empty plasmid) evoked significantly higher IL-1β secretion than did the Lro isolate transformed with the fadB4 plasmid, and the difference was greatest early after infection and in the absence of prestimulation with INF-γ." (PMID 36374090, 2022). "Remarkably, we found higher TNF, IL-1β, IL-6, and IL-10 in lung homogenates of LysM-cre × Hif1αfl/fl mice when compared with Hif1αfl/fl control mice at 12 hours after inoculation; these differences were not present anymore at 40 hours after infection." (PMID 34393650, 2021). "Prior clinical studies have shown higher levels of IL-1β and IL-8 in women with concurrent BV and TV as compared to women with neither infection; however, we show for the first time higher levels of galectin-1, RANTES, and IP-10 to be associated with incident TV in women with BV only." (PMID 34422675, 2021). "Therefore, while caspase-1 likely does not play a major role in cell death during infection with clinical P. aeruginosa isolates from CF patients, canonical inflammasome activation appears to play a role in IL-1β maturation and secretion." (PMID 33664232, 2021). "Furthermore, to address the effect of FMDV on NLRP3 inflammasome-mediated IL-1β production, we found that IL-1β secretion and protein maturation were impaired in PK-15 cells expressing shNLRP3 (short hairpin NLRP3, shNLRP3) after FMDV infection compared with control cells." (PMID 35062226, 2021). "The IL-1β mRNA levels showed no significant increase at any time point after infection." (PMID 33477869, 2021). "RT-qPCR and Western blot analysis showed that the levels of IL-1β, IL-6, TNF-α, and iNOS increased and mRNA and protein levels of TGM2 decreased in liver tissues of HFD-fed mice in comparison to control mice, while opposite results were observed by the further infection of AAV8-anti-miR-9-5p." (PMID 35261562, 2021). "In this regard, previous works have shown that cytosolic HBeAg can suppress IL-1β-mediated NF-κB activation and impair JAK-STAT signaling leading to the repression of interferon action, providing a molecular mechanism that also promotes persistence of infection." (PMID 34803982, 2021). "Furthermore, we could only identify a trend or correlation between levels of IL-1β expression and those of IL-6, CCL3 and CCL4 in the very early infection phase (3 h) and at high bacterial loads (MOI = 1:1000)." (PMID 33652921, 2021). "As with primary human macrophages, infections of THP-1 macrophages in vitro with early or chronic isolates of P. aeruginosa elicited significant differences in host cell death: Isolates from chronic infections induced less cell death and lower IL-1β expression than did early isolates." (PMID 33664232, 2021).
infection (continued). "We speculated that the increase in Cxcl1 levels rather than the decrease in IL-1β levels may account for the more severe infection in the GSDMD−/− mice." (PMID 34011393, 2021). "In addition, the levels of secreted IL-1β and IL-18 in the culture media remained at the basal level which did not change through the course of infection." (PMID 33796483, 2021). "Thus, IL-1β production by C8/108 mutants correlated closely with ASC speck formation (IL-1β:speck ratio of about 1) in response to Fn U112 infection, but was not correlated when nigericin was used." (PMID 34745125, 2021). "IL-1β was observed with a significant decrease in the supernatant of SFTSV infected NLRP3 KO THP-1 cells 48 h after infection compared with the wild type THP-1 cells, while no significant change of TNF-α and IL-6 was detected in the NLRP3 KO cells compared with wild type cells." (PMID 33708197, 2021). "In senescence-related susceptible individuals exposed to endogenous (genetics and epigenetics) stress and exogenous (environment and infection) injury, virus-induced NLRP3 inflammasome activation may drive the inflammation response by activating caspase-1 and production of mature IL-1β and IL-18." (PMID 34638790, 2021). "At this early time point post infection (30 min), neither Mtb nor the ΔpknF mutant alone induced any significant secretion of IL-1β These results suggest that in mouse macrophages, PknF plays an important role in inhibiting the activation of the NLRP3 inflammasome." (PMID 34324582, 2021). "The animals were sacrificed 96 hours and 2 weeks after infection, their lungs removed, macerated and the leukocytes analyzed by flow cytometry for the intracellular expression of IDO, AhR, and cytokines (IL-12, TNF-α, IL-1β, IL-6, TGB-β, and IL-10) by CD11c+ myeloid cells." (PMID 33936043, 2021). "Moreover, the expression of the cytokines IL-1β, IFN-γ, IL-6, TNF-α, and TGF-β was higher in HDV-∆L-HDAg mice than in HDV-WT at days 14 and 21 post-infection, in agreement with the increased liver damage observed at these time points; however, only the expression of TNF-α was significantly higher." (PMID 33925087, 2021). "In the present study, infection with S. hyicus (toxigenic strain and non-toxigenic strain) induced a robust IL-1β response, as indicated by the elevated serum IL-1β levels 6 h post infection in both toxigenic-strain-infected piglets and non-toxigenic-strain-infected piglets." (PMID 33665221, 2021). "In the brainstem, it was observed an increase of pro-inflammatory cytokines, such as IL-1β, IL-12(p70), IL-13, and TNF-α; chemokines, such as CCL2, CCL3, CCL4, CCL11, CXCL10, and CXCL1; growth factors, such as G-CSF, GM-CSF, M-CSF, and anti-inflammatory IL-10 at ten days post-infection." (PMID 33917837, 2021). "In this study, the relative expression levels of inflammatory cytokines TNFα, IL-8, IL-18, and IL-1β in IPEC-J2 cells along with the secretion of TNFα and IL-8 in the cell supernatant were significantly lower in the ΔhtpG infection group than those in the WT infection group." (PMID 34869065, 2021). "This suggests that the maximal rate of glycolysis early in response to infection and not the degree of change, may be an important factor in the subsequent production of mature IL-1β." (PMID 34691015, 2021). "BAPTA-AM failed to inhibit the production of IL-1β in BMDMs during ΔpknF mutant infection." (PMID 34324582, 2021). "Interestingly, we did not observe COX-2 expression in isolated fibroblasts after infection with S. suis, but after stimulation with recombinant IL1β." (PMID 33673302, 2021). "As IL1β, IL8, RANTES, and MCP-2 were reported as important factors related in severe symptoms, their high levels might be related with the immunopathology in acute phase of mild/moderate infection." (PMID 35095832, 2021). "Interestingly, blocking ESX-1 with the anti-virulence compound BTP15 several hours after infection strongly reduced IL-1β secretion without affecting intracellular IL-1β levels." (PMID 34718331, 2021).
infection (continued). "The levels of serum ALT, AST, liver IL-6, TNF-α, and IL-1β mRNA and liver pathological injury scores were further increased when pretreated with recombinant IL-27 in WT mice, but these levels were decreased in IL-27r−/− mice after CLP-induced severe infection compared to WT mice." (PMID 33564275, 2021). "Moreover, data showed that LP17 not only abrogated the significant difference in IL1β and TNFα expression, but also eliminated the apparent difference in CCL2 and CXCL10 expression between both groups of S. typhimurium-infected mice at 3 days post-infection." (PMID 33475464, 2021). "Moreover, in this in vivo model of infection, daily treatment (orally administered) with 25 mg/kg/day Bzl induced a significant decrease in IL-1β, IL-6 and NOS2 in the heart and CK activity in serum, to normal levels." (PMID 34925364, 2021). "Thus, significant amounts of IL-1β can still be released in Gsdmd-/- mice via GSDMD-independent macrophage lytic death to maintain host responses to C. albicans, thereby alleviating infection in these mice." (PMID 34795266, 2021). "Combined with the differences in IL-1β bioavailability, these results indicate that although R. parkeri, R. africae, and R. massiliae all replicate successfully within THP-1 macrophages, they trigger qualitatively and quantitatively distinct inflammatory responses during infection." (PMID 34935429, 2021). "It has recently been reported that the secretion of IL-1β induced by gram-negative pathogens such as Shigella and Pseudomonas aeruginosa when they infected macrophages is related to infection doses and time." (PMID 34869071, 2021). "Furthermore, BALB/c mice are representative of a chronic wound model, as their wounds are arrested in the inflammatory phase of wound healing, expressing continuously high levels of Interleukin-1β (IL-1β) besides the lack of ability to gain infection control." (PMID 32664205, 2020). "Furthermore, Nie shows that infection of mice with P. gingivalis induces the production of beta amyloid through the activation of CatB/NF-κB and the increase in the expression of TLR-2 and IL-1b." (PMID 32054121, 2020). "In addition to non-expression of inflammasome genes after 8 hours of infection, L. infantum neither activate caspase-1 nor determined IL-1β production in the three evaluated time-points, confirming that this platform was not indeed activated." (PMID 31961876, 2020). "Furthermore, we also showed that cytokines such as IL-1β, IL-6, TNF-α, IL-8, and IL-10 may act as indicators of a lethal outcome at the endpoint of the infection process." (PMID 33553280, 2020). "Our results suggest that IL-1β is not directly involved in the response to an L. fermentum treatment in C. jejuni-challenged chickens, especially during the first two days after pathogen infection." (PMID 32872452, 2020). "On the other hand, the increased expression of IL-1β, as a consequence of the inflammatory process induced by SARS-CoV-2 infection, may also contribute to the over-activation of ADAM17 in the early stage of the infection." (PMID 33117379, 2020). "Subsequently, we sought to examine the influence of Ss infection on the systemic levels of Type-1 (IFN-γ, TNF-α, and IL-2), Type-17 (IL-17A and IL-22), Type-2 (IL-4, IL-5, and IL-13), regulatory (IL-10) and pro-inflammatory cytokines (IL-1α, IL-1β, IL-6, IL-12, and GM-CSF) in INF and UN individuals." (PMID 33042134, 2020). "In contrast, only weak correlations were observed for Mφ2 (except for MIP-1α, IL-1β, and IL-8 upon TMP269 exposure), confirming a limited effect of exposure to low concentrations HDAC inhibitors during differentiation toward Mφ2 on cytokines/chemokines responses following infection with Mtb." (PMID 32117228, 2020).
infection (continued). "Secretion of proinflammatory mediators such as cytokines and chemokines (G-CSF, GM-CSF, IL-1α, IL1β, IL-6, IL-8, and CCL5) by epithelial cells, signal the recruitment of phagocytic cells, including neutrophils, macrophages and dendritic cells (DCs) to the site of infection." (PMID 31963180, 2020). "Similarly, in spleens from LCMV-infected RAG1 KO mice, there were no significant changes for TNF, IL-1β and IL-6 mRNAs post infection." (PMID 32310998, 2020). "IL-1β was not affected by infection (F1, 12 = 1.0, P = 0.35) or any first-order interactions, microbiota treatment × V. anguillarum exposure (F1, 12 < 0.1, P = 0.86), microbiota treatment × population (F1, 14 = 1.4, P = 0.25), and population × V. anguillarum exposure (F1, 12 = 1.0, P = 0.77)." (PMID 32970813, 2020). "Our previous studies show that infection with either P. vivax or P. falciparum prime circulating monocytes to express an inflammasome gene signature, form AIM2, NLRP3, and NLRP12 specks, express active caspase-1, and produce high levels of IL-1β, when challenged with LPS18,19,32." (PMID 32929083, 2020). "Similarly, IL-1β protein was significantly elevated post infection in both non-CF (4.4 ± 2.3 pg/mL vs. 20.9 ± 9.9 pg/mL; p < 0.05) and CF AEC (3.9 ± 3.6 pg/mL vs. 24.2 ± 18.7 pg/mL; p < 0.05) supernatant when compared to controls." (PMID 32328066, 2020). "Although there were no typical symptoms after infection, the expression of proinflammatory cytokines IL-1β, IL-6 and IL-8 were significantly induced at 5 dpi in lungs and at 7 dpi in spleen, and at the same time, the expression of anti-inflammatory cytokine IL-10 was also induced." (PMID 31992193, 2020). "However, the combination of simvastatin with DAPT produced a trend toward increasing levels of TNF-α and IL-1β without affecting IL-10 although these cytokines never reached the levels observed with the infection." (PMID 32393497, 2020). "In addition, it has been shown that infections by the H9N2 influenza virus strain, which originated from swine hosts, in BALB/c mice resulted in inflammation and injury in the lung with production of pro-inflammatory cytokines including TNFα, IL-1β and IL-6." (PMID 32709018, 2020). "However, other studies have shown that S. flexneri (strain YSH6000) infection induces IL-1β secretion in bone marrow-derived macrophages without LPS priming." (PMID 32582195, 2020). "Here we observed that elevated cytokines during Brucella infection in BS-treated mice including IL-12, TNF, IFN-γ, and IL-1β are important mediators of immune responses to intracellular pathogens, while MCP-1 also plays a central role in the maintenance of inflammation aimed to limit the infection." (PMID 31893609, 2020). "Regardless of the release mechanism, increased IL-1β, being a neutrophil chemoattractant, may further promote inflammation at sites of infection, supporting the hypothesis that covS mutant GAS promote greater levels of inflammation during GAS infection." (PMID 33585270, 2020). "Although Il1b induction (≈3-fold) remains modest compared to Il1b induction induced by NF-κB activation in BMDMs, IL-21 contributes to Il1b expression in vivo during Pneumonia Virus of Mice (PVM) infection, indicating that this production is likely relevant in specific contexts." (PMID 33138274, 2020). "Cells of the myeloid lineage—the primary source of IL‐1β in the body—do not express IL‐1β in the absence of inflammatory cues, and first need to transcriptionally upregulate its production in the context of infection or tissue damage." (PMID 32770571, 2020). "IL-1β, originating from avian macrophages, has been shown to elicit antiviral response and it is possible that IL-1β expression in lungs could have played a role in reducing IBV shedding early during the infection." (PMID 32326430, 2020). "However, the production of IL1B was not affected by IL10 knock-down during AF2122/97 infection at the mRNA or protein level." (PMID 31527895, 2019).
infection (continued). "In addition, infection of platelets with DENV leads to the assembly of the NLRP3 inflammasome, activation of caspase-1, and the production of IL-1β, which is secreted in microparticles and can promote increased vascular permeability, a phenomenon associated with the severity of the disease." (PMID 30901375, 2019). "IL-18 is believed to be directly involved in anti-infection and antitumour immunity and exerts negative feedback on IL-1β expression; on the other hand, IL-1β mainly induces inflammation injury by promoting the secretion of IFN-γ, IL-2 and GM-CSF by NK cells and T cells." (PMID 31827916, 2019). "Because IL-1β levels were also elevated in the brains of ZIKV-infected mice, we examined the possibility that IL-1β could mediate memory deficits induced by infection." (PMID 31488835, 2019). "We demonstrate that host-derived hypoxia signaling, mediated by the Hif-1α transcription factor, can prime macrophages with increased levels of Il-1β in the absence of infection, upregulating neutrophil antimicrobial NO production, leading to greater protection against infection." (PMID 30552162, 2019). "However, the systemic concentrations of some pro-inflammatory cytokines (IL-6 and CCL2), but not all (TNF-α, IL-1α, and IL-1β), were slightly over-induced in Ripk1LPC-KO mice at late stage of infection (72 hpi)." (PMID 30622241, 2019). "Infection with GBS ΔcylE mutants did not lead to elevation in THP-1 macrophage IL-1β production." (PMID 31737584, 2019). "Further studies in a mouse model of OVA-AAI, accompanied by infection with Chlamydia muridarum or Haemofilus influenza, demonstrated an increased expression of NLRP3 in airway epithelial and infiltrating immune cells, as well as enhanced IL-1β and caspase-1 mRNA levels in the lungs of infected mice." (PMID 31590215, 2019). "Consequently, we analyzed the mRNA levels of the proinflammatory cytokines TNF-α, IL-1β, and IL-6 and the anti-inflammatory cytokine IL-10, as well as the antimicrobial peptides TAP, DEFB1, and BNBD5 in LEAS-pretreated bMECs before and after infection." (PMID 31612151, 2019). "NF-κB is activated through a wide range of stimuli such as TNF-α, IL-1β and LPS and acts as a central regulator of the IEC innate immune response and as an essential transcription factor for integrating the pro-inflammatory response to infection with enteroinvasive bacteria." (PMID 31035617, 2019). "We hypothesized that this may be a part of an increased proinflammatory profile in innate immune cells; therefore, we tested whether Hif-1α is upregulating a proinflammatory program in the absence of infection using the il-1β:GFP transgenic line." (PMID 30552162, 2019). "Moreover, infection of human monocytic cell line with P. gingivalis activates NLRP3 and AIM2 inflammasome through caspase 1 activation, which produces the processing of pro-IL-1β to its active form IL-1β." (PMID 31049022, 2019). "In the lungs, the levels of proinflammatory cytokines, including interleukin-1β (IL-1β) and granulocyte colony-stimulating factor (G-CSF), and of chemokines, including IP10/CXCL10, MIP1-α/CCL3, MIP1-β/CCL4, MIP2/CXCL2, and KC/CXCL1, were increased and remained high after the infection with WT cells." (PMID 30940711, 2019). "Stabilization of Hif-1α upregulates il-1β transcription in macrophages in the absence of infection." (PMID 30552162, 2019). "-Downregulation of IL-6, IL-1β, and TNF-α -Cotreatment with 0.005 mg/g epinecidin-1 decreased the mortality rate upon infection. - 7 days after P. aeruginosa ATCC 19660 and P. aeruginosa R infection, the survival rate is 88.4% - All untreated mice died within 72 h of infection." (PMID 31824449, 2019). "MAYV infection in unprimed BMDMs triggered Il1b expression at 3 and 6 hours after infection, but it did not induce the release of significant levels of mature IL-1β." (PMID 31479495, 2019).